MMP9 (matrix metallopeptidase 9)
Diseases named in the same sentence as MMP9 in open-access papers (continued):
Sharing a sentence is not in itself a finding about the gene and the disease.
tumor (continued). "The scorbutic group tumors characteristically showed an irregular pattern of necrosis in tandem with MMP-9 expression that coincided with breaches in the tumor, creating conduits and channels for viable tumor cells to escape." (PMID 23175106, 2013). "In particular, the activities of MMP-2 and MMP-9 are often found to be elevated in tumor tissues and malignant cancer cells." (PMID 24223164, 2013). "In particular, MMP-2 and MMP-9 are collagenases and are crucial for tumor invasion and metastasis by degrading collagen IV." (PMID 23877152, 2013). "Studies using MMP-9 knockout mice have demonstrated that MMP-9 is essential for tumor vascularization and augments EPC mobilization and migration in a hindlimb ischemia model." (PMID 23555076, 2013). "Using our model we demonstrate that proteolysis is involved in tumor cell extravasation and highlight MT1-MMP and MMP-9 as important enzymes for the migration of different tumor cell types." (PMID 24194929, 2013). "There are many cytokines secreted by aHSCs that are associated with tumor invasion and metastasis, ingcluding HGF, EGF, IL-1, IL-2, IL-6, MMP-2, MMP-9, TGF-β, TNF-α, VEGF and Wnt families." (PMID 23622143, 2013). "Since MMP-2 and MMP-9 showed more tumor cell invasive activities than MMP-3, we focused on MMP-2 and -9 moving forward." (PMID 24324647, 2013). "Angiostatin produced from plasminogen by MMP7 and MMP9 has been shown to have biological activities such as inhibition of endothelial cell proliferation, angiogenesis, tumor growth and metastasis." (PMID 24216994, 2013). "Matrix metalloproteinases, especially MMP-2 and MMP-9, are also key regulators of tumor cell invasion and metastasis due to their ability to degrade type IV collagen, a major component of the ECM." (PMID 23900236, 2013). "Overexpression of EMMPRIN was found in many types of tumors, and was correlated to VEGF and MMP-9 induction and increased tumor invasiveness." (PMID 23874303, 2013). "While only MMP1 was associated with tumor differentiation, MMP3 and MMP9 were associated with ER−/PR− tumors." (PMID 23696797, 2013). "In the present study, we found that GLY not only attenuated enzyme activities and protein expression level of MMP-2 and MMP-9 in cell lysate, respectively, but also reduced MMP-2 and MMP-9 protein expression in tumor lysate (Supplemental S1)." (PMID 23573143, 2013). "Scorbutic tumors demonstrated large dark cores, associated with increased necrotic areas and breaches to the tumor surface, apoptosis and matrix metalloproteinase-9 (MMP-9), and weak, disorganized or missing collagen I tumor capsule." (PMID 23175106, 2013). "With both WM239 and MDA-MB231 cells undergoing transendothelial migration, MMP-9 was expressed at cell surface, but was also expressed in tumor cell ‘blebs’ (arrowheads)." (PMID 24194929, 2013). "Tumor cells excrete elevated levels of NGAL resulting in an increase of the local concentration of MMP-9, which is capable of affecting various aspects of tumor progression." (PMID 23760084, 2013). "The cytokine array data demonstrating production of numerous stromal-interacting cytokines (e.g. TIMP-1, MIF, uPA, Serpin E1/PAI-1, MMP-9) suggests that the xenografts are interacting with and being altered by components of the tumor microenvironment." (PMID 24204737, 2013). "As such, HRS cells that harbor the FGF2+/SDC1+ immunophenotype and express both MMP9 and TGFβ1 are the cells most likely to be shed from the tumor microenvironment." (PMID 23988031, 2013). "Next, western blotting was used to examine the expression of RABEX-5 and MMP-9 in transplantation tumor samples." (PMID 23941575, 2013). "The protein levels of Cyclin D1, Pro-Caspase-3, Bcl-2, MMP2 and MMP9 in tumor extracts were examined by western blot." (PMID 23874680, 2013). "Among various MMP types, MMP-2 and MMP-9 play pivotal roles in tumor cell invasion and metastasis by degradation of type IV collagen, a major component of the ECM." (PMID 24085323, 2013).
tumor (continued). "MMP-9 is a matrix metalloproteinase that was previously shown to play a critical role in the tumor microenvironment by enhancing cancer cell motility, angiogenesis and cancer growth." (PMID 23941575, 2013). "We then treated the embryos with an MMP-9 inhibitor (2 μM, AG-L-66085) (Santa Cruz Biotech) after injection of tumor cells and examined the invasiveness of tumor at 2 dpi." (PMID 23613942, 2013). "The increase in tumor malignancy and metastatic phenotype were attributed to the induction of MMP-9 expression by galectin-7." (PMID 23985992, 2013). "We also investigated variation in MMP9, as MMPs influence cancer progression and contribute to tumor angiogenesis, growth, and metastasis by degrading the extracellular matrix and activating growth factors." (PMID 23634849, 2013). "MMP-9 expressed on the tumour cell surface cleaves the IL-2 receptors of approaching cytotoxic lymphocytes, so preventing killing of the tumour cell." (PMID 23383108, 2013). "We also describe that tumor size reduction is a result of decreased MMP-9 expression, decreased angiogenesis, and increased apoptotic cells in tumors treated with AM9D." (PMID 23407024, 2013). "MMP-9 is a critical player in the early stages of tumor invasion by degrading basement membrane type IV collagen, considered to be a crucial step in tumor cell invasion." (PMID 23737761, 2013). "To clarify the inhibitory mechanism of tumor cell invasion, we examined the effect of ulinastatin on the activation of MMP-9 and plasminogens." (PMID 23710449, 2013). "The expression of MMP-9, one of the key players involved in tumor metastases and ‘premetastatic niche’ formation, was examined using immunohistochemistry." (PMID 23527047, 2013). "Cathepsin B, a cysteine protease, and MMP-9 have been shown to participate in tumor growth, invasion, and angiogenesis in GBM; RNA interference was effective in suppressing this phenotype, suggesting a potential therapeutic application." (PMID 23658650, 2013). "Here, we showed that the tumor cell invasive genes (e.g., MMP-9 and ICAM-1) were all suppressed by Ssd treatment." (PMID 23573150, 2013). "We have begun studies designed to determine the specific roles of MMP9 and CD44s in tumor progression." (PMID 23476138, 2013). "Collectively, our data implicate astrocyte-derived MMP-2 and MMP-9 as critical players that facilitate tumor cell migration and invasion leading to brain metastasis." (PMID 24324647, 2013). "These anti-tumor effects on OSCC are associated with the suppression of AKT and the repression of DNA-binding activities on MMP-2 and MMP-9 promoters." (PMID 23799155, 2013). "MMP-9, by degrading components of the extracellular matrix and thus promoting the release of growth factors, is important in tumor growth and tumorigenicity." (PMID 23760084, 2013). "Our results suggest that the BCL-6 pathway is disrupted as inflamed tissue transforms into tumor, with the possibility that loss of BCL-6 expression leads to increased cancer invasion via increased MMP-9 expression." (PMID 23737761, 2013). "Both high level of CypA and MMP9 expression significantly correlated with the tumor differentiation and metastasis." (PMID 24351116, 2013). "Immunohistochemistry was also used to determine the protein expression of RABEX-5 and MMP-9 in the tumor sections." (PMID 23941575, 2013). "MMP9 expression in tumor tissues also decreased when treated with Ad-si-IL-17 compared with Ad-SNC (P<0.05)." (PMID 23372655, 2013). "Because it remodels the extracellular matrix and promotes the sprouting and growth of new blood vessels by making VEGF available to the VEGFR-2/flk receptor on endothelial cells, MMP-9 is a linchpin in tumor progression." (PMID 23606867, 2013). "MMP-2 expression was observed in both large and small tumor cells, while MMP-9 expression was observed primarily in large tumor cells." (PMID 23536878, 2013).
tumor (continued). "This decrease in tumor growth was correlated with decreased MMP-9 protein production within the treated tumor tissues." (PMID 23407024, 2013). "Results obtained by qPCR showed a marked decrease in the expression of IL-8, PTHrP, TGF-β, RANKL, and MMP-9, all of which are involved in tumor cell invasion and skeletal metastasis." (PMID 24403228, 2013). "MMP-2 was present in both tumor and stromal cells; however, MMP-9 was present in stromal, vascular and perivascular cells surrounding nests of tumor cells." (PMID 23446555, 2013). "When tumor tissues were stained with MMP-9 antibody, costunolide inhibited a number of MMP-9 positive cells." (PMID 23997800, 2013). "The foci of tumor cells in the same core or tissue section which demonstrated intense staining for CD44s (d') and MMP9 (f') displayed minimal staining for CD44v6 at the periphery in the monolayer cells (b')." (PMID 23476138, 2013). "Factors significantly related to shorter DFS, shorter OS, tumour-related death and higher risk of recurrences/distant metastases included high MIB-1 LI and high uPA and MMP-9 expressions by tumour-adjacent fibroblasts." (PMID 23289974, 2013). "Growth rate, apoptosis, cell cycle parameters, and expression of mRNA for proteins associated with invasiveness and tumor microenvironment (CA IX, VEGF-A, HIF-1A, MMP-9, and TIMP-2) were analyzed." (PMID 23914349, 2013). "Taken together, these data show that AM9D efficiently decreases MMP-9 expression in tumors, resulting in the observed anti-tumor effects." (PMID 23407024, 2013). "Several reports have implicated cytokines, chemokines, hypoxia-inducible 1, integrin, and MMP-9 in regulating tumor angiogenesis." (PMID 23714001, 2013). "Up-regulation of Smo increased transcription of Gli1 and MMP9 which led to increased tumor cell invasiveness." (PMID 23880852, 2013). "The activity of MMP-9 in tumor cell extravasation was investigated using a function-blocking antibody." (PMID 24194929, 2013). "MMP-9 has been shown to play a role in tumor progression through increase of bioavailability of VEGF and other factors that promote angiogenesis." (PMID 23407024, 2013). "Elevated hydrostatic pressure and acidic media each enhanced mRNA expression of MMP-9 in tumor cells." (PMID 23914349, 2013). "Next, we investigated the effect of ZD6474 and UV-B on the secretion of MMP-9, which is believed to play an important role in tumor invasion." (PMID 24138843, 2013). "MMP-9 has also been shown to trigger an angiogenic switch during tumor progression by releasing matrix-bound VEGF, making the latter available for interaction with VEGF receptors." (PMID 23383216, 2013). "The tumor-promoting function of MDSC is associated with increased activities of Arg-1, MMP9, and S100A8." (PMID 24453427, 2013). "MCP-1/CCL2 can also stimulate macrophages to secrete urokinase-type plasminogen activator (uPAR) and MMP-9, both of which have the ability to remodel the tumor ECM." (PMID 24314323, 2013). "On the other hand, IHC study revealed that the macrophages in the tumor microenvironment were slightly positive for MMP-9 in samples of DLBCL and FL samples." (PMID 24236041, 2013). "The IL-6 silencing vector increased expression of E-cadherin associated with decrease in vascular endothelial growth factor (VEGF) and matrix metallopeptidase 9 (MMP-9) expressions in tumor cells." (PMID 23637926, 2013). "MMP-9 has been implicated in ECM degradation, angiogenesis, and subsequent tumor growth and invasion." (PMID 24325546, 2013). "Given that CTSB is proteolytic enzyme expressed at high levels in vasculature during vBM degradation associated with tumor angiogenesis, CTSB promotes the degradation of vBM together with other proteolytic enzyme such as MMP9 in SSc." (PMID 22384200, 2012). "Reduced S100A4 and MMP9 expression was confirmed on protein level by immunohistochemistry of tumor tissue from both groups." (PMID 22878175, 2012).
tumor (continued). "Considering stimulation, membrane type-1 MMP (MT1-MMP), also known as MMP14 is one of main activators, and also Interleukin-8 (IL-8) upregulates MMP2 and MMP9 in tumor cells, which is thought to be responsible for its angiogenic activity." (PMID 22695075, 2012). "In our recent immunohistochemical study, we found that EMMPRIN expression in SACC was positively-associated with tumor perineural and perivascular invasion, and that MMP-2 and MMP-9 were expressed both in the tumor and stromal compartments." (PMID 22200897, 2012). "Matrix metalloproteinase-9 (MMP-9) and urokinase plasminogen activator receptor (uPAR) are over expressed in several cancers and well established for their roles in tumor progression." (PMID 22984561, 2012). "The cytokine IL-23 is considered to promote tumor incidence and growth by upregulating MMP9, thereby stimulating inflammatory responses." (PMID 22778768, 2012). "In general, LRP1 modulates MMP9 expression and low level of LRP1 in HCC cells is associated with tumor aggressiveness in HCC." (PMID 22427881, 2012). "Tumor-associated macrophages of the tolerogenic “M2” phenotype drive angiogenesis by secreting VEGF, MMP9, epidermal growth factor (EGF), and interleukin-8 (IL8)." (PMID 22312408, 2012). "Previous studies suggested that MMP-9 expression were closely related to tumour angiogenesis than MMP-2." (PMID 23107277, 2012). "In PCa cell line DU-145 miR-21 showed that directly inhibits RECK, a tumor suppressor gene that is involved in the control of MMP9." (PMID 22642976, 2012). "Another mechanism by which lipocalin-2 can convey a metastatic potential to tumor cells has been proposed to relate to the possible activating or stabilizing effect of lipocalin-2 on MMP-9." (PMID 22737251, 2012). "The present study demonstrates that low expression of LRP1 is a major contributor to the invasion-prone phenotype of HCC, and inhibition of LRP1, coupled to the increased expression and bioactivity of MMP9, enhances tumor cell migration and invasion." (PMID 22427881, 2012). "Matrix metalloproteinases, especially MMP-2 and MMP-9 play pivotal roles in tumor cell invasion and metastasis due to their ability to degrade type IV collagen, a major component of the ECM." (PMID 22736175, 2012). "Further, immunohistochemical staining of MMP-9 in CRC specimens showed strong positivity in tumor cells and confirmed that tumor associated macrophages are important source of MMPs during the carcinogenic process." (PMID 22848630, 2012). "Growth in number of studies implicating multiple roles of uPAR and MMP-9 in regulating extracellular matrix dissolution, activating growth factor, initiating intracellular signaling leading to tumor progression and metastasis are increasing day by day." (PMID 22984561, 2012). "In Dukes’ B tumours, MMP-9 positivity was an independent prognostic factor (p = 0.034), as was tumour location (p = 0.041)." (PMID 23216739, 2012). "MMPs, especially MMP-2 and MMP-9 play key roles in tumor cell invasion and metastasis due to their ability to degrade type IV collagen, a major component of the ECM." (PMID 22736175, 2012). "Several molecules/factors secreted by TAMs such as MMP-9, IL-23, IL-10 facilitate tumor cell proliferation thereby limiting the cytotoxicity of the microenvironment." (PMID 23316105, 2012). "For this study, the oncolytic vaccinia virus GLV-1h255, containing the mmp-9 gene, was constructed and used to treat PC-3 tumor-bearing mice, achieving an intra-tumoral over-expression of MMP-9." (PMID 22917220, 2012). "Taken together, these results indicate that a GLV-1h255-mediated intra-tumoral over-expression of MMP-9 leads to a degradation of collagen IV, facilitating intra-tumoral viral dissemination, and resulting in accelerated tumor regression." (PMID 22917220, 2012).
tumor (continued). "Although difficult to explain, a recent study has reported pro-metastatic effects induced by MMP9 in tumor cells and bone marrow derived cells in mouse xenografts after exposure to certain chemotherapies (taxane-based)." (PMID 23056490, 2012). "In particular, MMP9 has been identified as a significant molecule contributing to tumor cell metastasis." (PMID 22200787, 2012). "High tumour and stromal MMP-2 and MMP-9 expression was significantly associated with positive lymph node status." (PMID 23107277, 2012). "We therefore examined the effect of sLRP6E1E2 on expression of MMP-2 and MMP-9, which play a critical role in angiogenesis, tumor growth, and metastasis." (PMID 22606268, 2012). "In a study of 188 subjects, high MMP-9 levels were significantly correlated with large tumor size and poor malignancy grade, and increasing levels were associated with poor overall survival." (PMID 22559832, 2012). "We also examined the expression of MMP2 and MMP9, which are known to play a role in tumour invasiveness, LVI and induce angiogenesis in several types of cancer." (PMID 23304558, 2012). "In particular, relief of the repression of the matrix metalloproteinase MMP9 expression by SM22 in tumour cells where SM22 is downregulated would lead to increased MMP9 levels." (PMID 22257561, 2012). "Tumor invasion is regulated by numerous NF-κB target gene products, including MMP-9, TIMP-1/2, PAL 2, CXCR4, interleukin-8 (IL-8), and other chemokines." (PMID 22776619, 2012). "Proteins like matrix metalloproteinase 2 (MMP2), MMP9 and serine protease urokinase-type plasminogen activator (uPA) which play an important role in tumour invasion and metastasis, are under the transcription control of NFκB." (PMID 23905066, 2012). "Almost all of the tumour samples showed an unmethylated MMP-9 pattern in conjunction with increased mRNA levels." (PMID 22866959, 2012). "MMP-2 (gelatinase A) and MMP-9 (gelatinase B) play important roles in destroying the basement membrane of tumor vessels, and their expression correlates with metastasis." (PMID 22159401, 2012). "GLV-1h255-treatment of PC-3 tumors led to a significant over-expression of intra-tumoral MMP-9, accompanied by a marked decrease in collagen IV content in infected tumor areas, when compared to GLV-1h68-infected tumor areas." (PMID 22917220, 2012). "Consistent with our in vitro results, tumor sections from mice treated with the shRNA constructs showed decreased staining for uPAR and MMP-9 as compared to pSV-treated tumors." (PMID 22984561, 2012). "For MMP-9, we found a bivalent correlation between MMP-9 expression and survival, that is, patients with either very low or very high MMP-9 tumour protein levels have worse survival compared with patients with intermediate MMP-9 expression." (PMID 22472880, 2012). "The effect of sera derived from TG and WT mice on the transcription and expression of VEGF, IL-8 and MMP-9 in tumor cells was then assessed, since these molecules play key roles in the process of tumorigenesis and metastasis." (PMID 23226476, 2012). "Expression of MMP-9 and MMP-2 has been implicated in the development and progression of many neoplasias, such as prostate, colorectal and lung cancer." (PMID 22695075, 2012). "AD cells had high expression of MMP2 and MMP9, proteases involved with matrix remodeling during tumor dissemination." (PMID 23056490, 2012). "Another important finding of our study was the relationship between MMP-9 and IL-8 higher levels and tumor recurrence during a long follow-up period (mean of 40 months)." (PMID 22695075, 2012). "As tumours progressed, MMP-9 expression increased in tumour epithelium and stroma, while the changes in MMP-2 expression in tumour cells was not as obvious as MMP-9." (PMID 23107277, 2012).